HOXC8 (homeobox C8)
Diseases named in the same sentence as HOXC8 in open-access papers (continued):
Sharing a sentence is not in itself a finding about the gene and the disease.
gastric cancer (continued). "Collectively, our results revealed that a complex interaction networks of differentially expressed genes in gastric cancer, and further functional studies indicated that miR-4256/HOXC8 may be an important axis in regulating gastric cancer progression." (PMID 35111675, 2021). "Consistently, these results implied that HOXC8 may act as an oncogene to promote the progression of gastric cancer cells." (PMID 35111675, 2021). "Furthermore, we also performed in vitro functional studies to determine the potential role of the miR-4256/HOXC8 axis in modulating the progression of gastric cancer." (PMID 35111675, 2021). "Therefore, in this study, we focused on HOXC8 to further investigate gastric cancer." (PMID 37670969, 2023). "Moreover, HOXC8 knockdown reduced cell proliferation in gastric cancer." (PMID 37670969, 2023). "We further confirmed whether there was HOXC8-mediated SPP1 expression in gastric cancer cells." (PMID 37670969, 2023). "Thus, we firstly examined if HOXC8 was dysregulated in the gastric cancer cells." (PMID 35111675, 2021). "The functional studies indicated that HOXC8 may exert oncogenic effects on gastric cancer." (PMID 35111675, 2021). "In this study, we further evaluated the effect of HOXC8 on the expression of OPN and the AKT/ERK pathway in gastric cancer cells." (PMID 37670969, 2023). "This study is the first to investigate the molecular mechanism by which HOXC8 modulates cell growth, colony formation, and the OPN-related pathway of gastric cancer cells." (PMID 37670969, 2023). "HOXC8 modulated the expression of secreted phosphoprotein 1 (SPP1, osteopontin) and phosphorylation of AKT/ERK in gastric cancer cells." (PMID 37670969, 2023). "HOXC8 knockdown significantly inhibited the expression of OPN and the phosphorylation of AKT/ERK in gastric cancer cell lines." (PMID 37670969, 2023). "In our study, HOXC8 knockdown significantly inhibited the cell growth and colony formation, and decreased the expression of OPN in gastric cancer cells." (PMID 37670969, 2023). "We revealed that HOXC8 knockdown reduced the expression of OPN and phosphorylation of AKT/ERK in gastric cancer cells." (PMID 37670969, 2023). "HOXC8 knockdown significantly reduced the phosphorylation of AKT and ERK in gastric cancer cells." (PMID 37670969, 2023). "Although HOXC8 reportedly mediate cell viability in gastric cancer cell lines 36, the role of HOXC8 in gastric cancer has not been fully evaluated." (PMID 37670969, 2023). "Knockdown of HOXC8 and overexpression of miR-4256 both significantly repressed the gastric cancer cell proliferation and migration, and miR-4256 repressed the expression of HOXC8 via targeting its 3’UTR in gastric cancer cells." (PMID 35111675, 2021). "Based on the literature research, several members of the HOXC family have been well studied for their role in gastric cancer, however, HOXC8 has not been fully elucidated for its role in regulating gastric cancer progression." (PMID 35111675, 2021). "We could not exclude the possibility that HOXC8 directly or indirectly modulates OPN expression; however, this is the first study to evaluate alterations in HOXC8 and OPN expression in gastric cancer cells." (PMID 37670969, 2023). "However, the mechanism by which HOXC8 modulates OPN expression and regulates the malignant phenotype of gastric cancer cells has not been clearly elucidated." (PMID 37670969, 2023).
lung carcinoma (3 papers, 2018 to 2025). "We found that HOXC8 contributed to NSCLC cell proliferation, anchorage-independent and migration via regulating TGF-β1 expression, and high expression of HOXC8 was associated with aggressive phenotypes and poor relapse free survival for lung cancer patients." (PMID 29367650, 2018). "Furthermore, gain- and loss-of-function experiments indicated that HOXC8 expression promoted the proliferation, anchorage-independent cell growth and migration of lung cancer cells." (PMID 29367650, 2018). "Importantly, high expression of HOXC8 was linked to poor relapse-free survival for lung cancer patients." (PMID 29367650, 2018). "In future study, we will investigate the effect of HOXC8 siRNAs on antitumor immunity in LKB-null lung cancer models including patient-derived organoids and immunocompetent mice." (PMID 40701951, 2025). "Analysis of The Cancer Genome Atlas (TCGA) lung cancer datasets revealed that HOXC8 expression was significantly higher in NSCLC that included both lung adenocarcinoma (LUAD) and lung squamous cell carcinoma (LUSC), compared with corresponding normal tissue." (PMID 40701951, 2025). "Bioinformatics analysis revealed that caspase-1 expression is generally lower in lung cancer and is inversely correlated with HOXC8 expression." (PMID 40701951, 2025). "To determine the role of HOXC8 in lung cancer cells, we carried out experiments to knockdown HOXC8 expression or ectopically express HOXC8 in NSCLC cell line A549 or NCI-H460." (PMID 29367650, 2018). "Consistently, we further showed that knockdown of HOXC8 significantly inhibited proliferation, anchorage-independent cell growth and migration of lung cancer cells, which can be rescued by ecto-expression of TGFβ1." (PMID 29367650, 2018). "In MTT assays, silencing HOXC8 significantly reduced lung cancer cell proliferation as shown by the growth curves, and ectopic expression of HOXC8 markedly increased the proliferation of A549 or NCI-H460." (PMID 29367650, 2018). "Given the fact that HOXC8 regulates TGFβ1 transcription in lung cancer cells, we analyzed the effects of TGFβ1 on cell proliferation, anchorage-independent cell growth and cell migration in A549 and NCI-H460 cells." (PMID 29367650, 2018). "The ability of HOXC8 knockdown to trigger pyroptosis in lung cancer cells indicates that delivery of HOXC8 siRNA may possess tumor-inhibitory capability." (PMID 40701951, 2025). "Finally, to investigate the role of HOXC8 in migration of lung cancer cells, we performed transwell migration assays." (PMID 29367650, 2018). "Hence, we speculate that pyroptosis caused by HOXC8 knockdown in LKB-null lung cancer cells could simultaneously kill cancer cells and convert non-immunogenic tumor to immunogenic one." (PMID 40701951, 2025). "Especially, we will investigate the potential of using lipid-conjugated or nanoparticle-delivered HOXC8 siRNA to boost the efficacy of immune checkpoint blockers such as anti-PD1 and anti-PD-L1 in LKB-null lung cancer models." (PMID 40701951, 2025). "Our finding that depleting HOXC8 triggers pyroptosis in A549 and H460 cells is of a particular interest, as both cell lines are LKB-null and LKB-null lung cancer is generally unresponsive to immunotherapy." (PMID 40701951, 2025). "All these data suggested that HOXC8 expression was elevated in NSCLC and played an important role in lung cancer development." (PMID 29367650, 2018). "Surprisingly knockdown of ASC did not prevent cell death induced by HOXC8 depletion in lung cancer cell lines." (PMID 40701951, 2025). "Quantitative real‐time RT‐PCR (qRT‐PCR) analyses of total RNA isolates generated from directly ex vivo isolated normal lung or lung carcinoma tissues revealed a significant upregulation of HOXB7 and HOXC6, as well as HOXC8 mRNA by tendency expression in the NSCLC tissues." (PMID 32830458, 2021).
lung carcinoma (continued). "From the three MSC‐specific HOX candidates, HOXC8 was also found to be upregulated in clinical NSCLC specimens, and the high expression of HOXC8 correlated with tumor grade, tumor node metastasis stage, and poor relapse‐free survival for lung cancer patients." (PMID 32830458, 2021). "We showed that HOXC8 was upregulated in clinical NSCLC specimens compared to normal lung tissues, and the high expression of HOXC8 correlated with tumor node metastasis (TNM) stage, tumor status, lymph nodal status and poor relapse-free survival for lung cancer patients." (PMID 29367650, 2018).
melanoma (3 papers, 2014 to 2021). A malignant, usually aggressive tumor composed of atypical, neoplastic melanocytes. "Likewise, in melanoma, miR-196a inhibits the processes of proliferation and metastasis through the negative regulation of transcription factor HOXC8." (PMID 32711415, 2020).
pancreatic ductal adenocarcinoma (3 papers, 2011 to 2021). An infiltrating adenocarcinoma that arises from the epithelial cells of the pancreas. "This study was to investigate the role of HOXC8 in pancreatic ductal adenocarcinoma (PDAC) growth and metastasis." (PMID 21712827, 2011).
clear cell renal carcinoma (2 papers, 2021 to 2022). A malignant epithelial neoplasm of the kidney characterized by the presence of lipid-containing clear cells within a vascular network. "Moreover, a decreased HOXC8 and HOXC9 genes expression, as a classical white adipocytes signature, has been detected in perirenal fat in patients with clear cell renal carcinoma when compared to healthy people, while TBX1, TMEM26, or CD137 expression was unchanged." (PMID 33800984, 2021).
colorectal cancer (2 papers, 2014 to 2017). A primary or metastatic malignant neoplasm that affects the colon or rectum. "In colorectal cancer, miR-196a inhibited the expression of HOXA7, HOXB8, HOXC8 and HOXD8 genes, leading to AKT pathway activation and increased cell motility." (PMID 29259267, 2017).
esophageal squamous cell carcinoma (2 papers, 2013 to 2020). Esophageal squamous cell carcinoma (ESCC) is a type of esophageal carcinoma (EC) that can affect any part of the esophagus, but is usually located in the upper or middle third. "Deregulated expression of HOX genes including HOXB8, HOXC8, HOXD8 and HOXA7 in esophageal squamous cell carcinoma have been reported, and miR-196a is significantly up-regulated in pancreatic, breast, and esophageal cancer." (PMID 23967217, 2013).
invasive breast carcinoma (2 papers, 2014 to 2017). A carcinoma that infiltrates the breast parenchyma. "In this study, we demonstrated for the first time that ILF3 interacted with HOXC8 to activate CDH11 transcription in invasive breast cancer cells." (PMID 29296180, 2017). "We previously reported that knockdown of HOXC8 led to the reduction in CDH11 expression in invasive breast cancer cells." (PMID 24810778, 2014).
lung adenocarcinoma (2 papers, 2023 to 2025). A carcinoma that arises from the lung and is characterized by the presence of malignant glandular epithelial cells. "Through the analysis of HOXC8 expression in various cancer types, we revealed that HOXC8 is preferentially overexpressed in lung adenocarcinoma compared to normal lung tissue." (PMID 40701951, 2025). "To investigate the potential role of HOXC8 in lung adenocarcinoma, we found that depletion of HOXC8 led to pyroptosis." (PMID 40701951, 2025). "The early-stage lung adenocarcinoma (LUAD) prognostic model was constructed through the cancer genome atlas (TCGA) database, and three target genes (MMP12, NFE2, HOXC8) were screened to calculate the risk score of early-stage LUAD." (PMID 36650426, 2023).
metastatic tumour (2 papers, 2011 to 2017). "In primary and metastatic tumour samples, immunohistochemical staining for HOXC8 was stronger in surrounding than in neoplastic tissues." (PMID 21712827, 2011).
arthrogryposis (1 paper, 2022). A rare, non-progressive congenital disorder characterized by multiple joint contractures which are present at birth. "In addition, the HOXC8 gene has been associated with vertebral development in mice, myogenesis in Korean Hanwoo cattle, kyphosis and arthrogryposis multiplex congenital (AMC) in pigs, and the multi-vertebral number trait in Mongolian sheep." (PMID 36421849, 2022).
bladder cancer (1 paper, 2023). "The overexpression of HOXC8 reversed the proliferation and migration inhibition of bladder cancer cells induced by the suppression of circNT5E expression." (PMID 37627900, 2023).
carcinoma of the lip (1 paper, 2022). "HOXA5, HOXB9, HOXC8, HOXC10, and HOXC11 genes were specific to certain sites of the oral cavity whereas HOXA10 was associated with the development of the carcinoma of the lip and oral cavity." (PMID 35710803, 2022).
cervical adenocarcinoma (1 paper, 2025). An adenocarcinoma arising from the cervical epithelium. "Thirteen genes were found to be differentially expressed in cervical adenocarcinoma samples using microarray databases and literature reports, but only the MACC1, HOXC8, BCL2, and RARβ genes were the most representative of the expressed genes." (PMID 40361484, 2025). "We hypothesize that, even with the small number of samples used (randomized selection), there is strong evidence that the selected genes, HOXC6, HOXC8, RARβ, BCL2, and E6/E7, can be used as a pan early cervical adenocarcinoma test." (PMID 40361484, 2025). "In conclusion, this exploratory pilot study, through its robust and holistic analysis, provides evidence that MACC1, HOXC8, RARβ, BCL2, and E6/E7 could be promising molecular markers for the detection of cervical adenocarcinomas." (PMID 40361484, 2025).
chordoma (1 paper, 2021). Chordomas are rare malignant tumors arising from embryonic remnants of the notochord in axial skeleton. "Furthermore, HOXC8 overexpression has been shown to promote proliferation, colony formation, and cell invasion in the recurrent chordoma derived cell lines U-CH1 and U-CH2." (PMID 34330313, 2021).
coronary artery disease (1 paper, 2022). "The homeobox protein Hox-C8 (Hoxc8), a sequence-specific TF that is part of a developmental regulatory system that provides cells with specific positional identities along the anteroposterior axis and is related to proinflammatory and immunological genes and pathways in coronary artery disease." (PMID 35637715, 2022).
fractures (1 paper, 2022). "The signals in the other four genomic loci associated with hip fractures (REST, HOXC8, SALL1, and ETS2) were previously shown to associate with different BMD measures, supporting the notion that BMD is an important determinant also of hip fracture risk." (PMID 36260985, 2022).
gastric adenocarcinoma (1 paper, 2023). "A previous bioinformatics analysis revealed that HOXC genes (HOXC8, HOXC9, HOXC10, HOXC11, HOXC12, and HOXC13) might participate in pathogenesis of gastric adenocarcinoma." (PMID 37724126, 2023).
Hypertension (1 paper, 2023). The presence of chronic increased pressure in the systemic arterial system. "Multiple HOXC genes: HOXC-AS1-3, HOXC4, HOXC5, HOCX6, HOXC8, HOXC9 and HOXC10 were also shared between subsets of GORD, hypertension and precordial pain." (PMID 37410157, 2023).
influenza (1 paper, 2022). An acute viral infection of the respiratory tract, occurring in isolated cases, in epidemics, or in pandemics; it is caused by serologically different strains of viruses (influenzaviruses) designated A, B, and C, has a 3-day incubation period, and usually lasts for 3 to 10 days. "Because the encoded HoxC8 and HoxC6 proteins promote IAV replication, active loop formation at the HoxC8-HoxC6 loci, as a consequence of NP-dependent disruption of the Suv4-20h2-cohesin interaction, contributes to influenza-induced pathology (right)." (PMID 36398441, 2022).
metabolic syndrome (1 paper, 2022). A cluster of metabolic risk factors for CARDIOVASCULAR DISEASES and TYPE 2 DIABETES MELLITUS. "Examples of validated variants within microRNAs included in this catalog are miR-196a2 variant rs11614913 regulating SFMBT1 and HOXC8 in metabolic syndrome, and miR-4513 variant rs2168518 regulating GOSR2 in cardiometabolic diseases." (PMID 35365203, 2022).
MRKH syndrome (1 paper, 2021). "We then focused our attention on the expression of other genes selected from the literature which are likely to play a role in MRKH syndrome phenotype determination: MUC1, HOXC8 and GREB1L." (PMID 34063745, 2021). "In order to establish a correlation between MRKH syndrome phenotype and gene expression pattern, we performed PCA on data from RT-qPCRs for PRKX, MUC1, HOXC8 and GREB1L loci." (PMID 34063745, 2021).
oesophageal cancer (1 paper, 2019). "Considering the mechanism by which IL‐11 influences cancer has been thoroughly studied, we aimed to investigate the mechanism by which HOTAIR acting as a ceRNA of miR‐204 regulates the expression of HOXC8 in oesophageal cancer cells." (PMID 31389660, 2019). "Accumulating studies have highlighted long non‐coding RNA (lncRNA) HOX transcript antisense RNA (HOTAIR), microRNA‐204 (miR‐204) and homeobox C8 (HOXC8) in the progression of oesophageal cancer." (PMID 31389660, 2019). "Herein, we tried to demonstrate the function of HOTAIR, miR‐204 and HOXC8 in oesophageal cancer and their relationship." (PMID 31389660, 2019). "miR‐204 was down‐regulated, while HOTAIR and HOXC8 were up‐regulated in the oesophageal cancer tissues." (PMID 31389660, 2019). "The oesophageal cancer cells treated with si‐HOTAIR or miR‐204 mimic exhibited decreased expression levels of HOXC8, Vimentin and MMP‐9, but increased E‐cadherin level." (PMID 31389660, 2019). "To conclude, this study illustrated that lncRNA HOTAIR could function as a ceRNA of miR‐204, and the silencing of HOTAIR could reduce expression of HOXC8, which ultimately inhibited the proliferation, migration and invasion of oesophageal cancer cells." (PMID 31389660, 2019). "Thus, silencing of HOTAIR could suppress the expression of HOXC8 via miR‐204 and inhibit proliferation, migration and invasion while inducing apoptosis of oesophageal cancer cells." (PMID 31389660, 2019). "Our results revealed that miR‐204 was poorly expressed in the oesophageal cancer tissues while HOTAIR and HOXC8 were highly expressed." (PMID 31389660, 2019). "The endogenous expression of HOTAIR and miR‐204 in oesophageal cancer cell lines was altered to elucidate their effects and to identify the interaction among HOTAIR, miR‐204 and HOXC8." (PMID 31389660, 2019). "Immunohistochemistry and RT‐qPCR were conducted in order to determine the expression pattern of HOXC8, HOTAIR and miR‐204 in the oesophageal cancer tissues as well as the adjacent normal tissues." (PMID 31389660, 2019).
osteosarcoma (1 paper, 2021). A usually aggressive malignant bone-forming mesenchymal neoplasm, predominantly affecting adolescents and young adults. "HOXC8 could be targeted by miR-196a-5p and promote the cell growth of osteosarcoma." (PMID 35111675, 2021).
pancreatitis (1 paper, 2011). Inflammation of the pancreas. "This pictures a factor, which shows low expression in normal tissue, is up-regulated in premalignant tissue and pancreatitis, but low again in metastatic tissue, thus possibly suggesting a temporal role for HOXC8 expression in tumour progression." (PMID 21712827, 2011).
renal cell carcinoma (1 paper, 2025). "In addition, the PRAT browning process has been specifically detected in renal cell carcinoma (RCC), being characterized by upregulated expression of brown/beige adipocytes markers (UCP1, PPAR-ɣ, c/EBPα, and PGC1α) and downregulated white fat cells markers, such as LEPTIN, SHOX2, HOXC8, and HOXC9." (PMID 40227577, 2025).